CYP4B1 (cytochrome P450 family 4 subfamily B member 1)
Diseases named in the same sentence as CYP4B1 in open-access papers (continued):
Sharing a sentence is not in itself a finding about the gene and the disease.
adrenocortical cancer (2 papers, 2023 to 2025). "In a study, CYP4B1 expression was markedly suppressed in adrenocortical carcinoma (ACC), with almost complete silencing observed in both adenomas and carcinomas." (PMID 40723371, 2025). "Other studies sporadically describe the influence of CYP4B1 in other cancer types including adrenocortical carcinoma, prostate cancer, and breast and ovarian cancer." (PMID 36768362, 2023). "In adrenocortical carcinoma, CYP4B1 expression was shown to be nearly absent, while CYP4B1 expression in adrenocortical adenomas was shown to be significantly reduced compared to normal adrenocortical samples." (PMID 36768362, 2023).
bladder urothelial carcinoma (2 papers, 2022 to 2025). "CYP4B1 was lowly expressed in high-grade bladder urothelial carcinoma." (PMID 35807355, 2022). "CYP4B1 and CYP4F12 display low expression in normal bladder tissue and are detectable in certain cases of bladder urothelial carcinoma (BLCA), as reported by the Human Protein Atlas." (PMID 40723371, 2025).
colitis (2 papers, 2015). Inflammation of the colon. "Caffeic acid has been recently shown to increase the expression of CYP4B1 mRNA in DSS-treated mice and effectively inhibited DSS-induced murine colitis." (PMID 26042672, 2015).
Lung Squamous Cell Carcinoma (2 papers, 2022 to 2025). "An analysis of TCGA-lung squamous cell carcinoma (LUSC) data revealed that elevated CYP4B1 expression in LUSC correlated with reduced overall survival." (PMID 40723371, 2025).
adrenal cancer (1 paper, 2020). A carcinoma involving a adrenal gland. "The prognosis of LUAD, CESC and KIRC patients with low expression of CYP4B1 is poor, which is consistent with the findings of urethral cancer and adrenal cancer." (PMID 33195408, 2020).
cardiac hypertrophy (1 paper, 2025). "CYP4B1 overexpression attenuated angiotensin-II–induced cardiac hypertrophy and inhibited the migration, invasion, and proliferation of LC cells." (PMID 40924729, 2025). "Among hypertrophy-related genes (ANP, BNP, β-MyHC, COL1A1), only BNP mRNA levels significantly increased (1.9-fold; p < 0.01), while CYP4B1 expression was suppressed, suggesting its inhibitory role in cardiac hypertrophy." (PMID 40924729, 2025).
colon adenocarcinoma (1 paper, 2025). "The available data indicate that CYP4B1 expression is very low in colon adenocarcinoma (COAD) tissues." (PMID 40723371, 2025).
COVID-19 (1 paper, 2025). A disease caused by infection with severe acute respiratory syndrome coronavirus 2. "Consequently, the research pinpointed four key genes, MBP, CYP4B1, ERMN, and SLC26A7, which hold clinical relevance and exhibit potential significance in the pathophysiology of COVID-19 induced depression." (PMID 40918512, 2025).
dysplasia (1 paper, 2021). A usually neoplastic transformation of the cell, associated with altered architectural tissue patterns.
endometriosis (1 paper, 2021). The growth of functional endometrial tissue in anatomic sites outside the uterine body. "In addition, some identified hub genes of the EC (TAGLN, GATA6, CDH3, CLU, COL8A1, MYH11, MYOCD) and EU (CXCL13, DDK-1, KLF4, CYP2E1, CYP4B1 and PROK1) have been reported be associated with endometriosis." (PMID 34522169, 2021).
hypospadias (1 paper, 2020). Hypospadias is the displacement of the urethral meatus on the ventrum of the penis. "We identified a significant causal effect of methylation at cg04714159 on hypospadias, as well as potential causal effects of multiple members of the cytochrome P450 family of enzymes in this region (CYP4A11, CYP4A22, CYP4B1, CYP4X1, CYP4Z2P)." (PMID 32728162, 2020).
lupus (1 paper, 2023). "In this study, we subjected the autoimmune-prone MRL mice to BaP exposure before lupus onset and found that the kidneys were a major organ directly affected by the metabolism of benzene-containing compounds, with the increased expression of BaP-target genes including Cyp4b1 and Hao2." (PMID 37047136, 2023).
prostate adenocarcinoma (1 paper, 2025). "In a study of prostate adenocarcinoma (PRAD), the expression of CYP2A6, CYP3A5, and CYP4B1 genes was evaluated in prostate tissue using real-time quantitative PCR (RT-qPCR)." (PMID 40723371, 2025).
prostate carcinoma (1 paper, 2023). A carcinoma that arises from epithelial cells of the prostate gland. "CYP4B1 mRNA was also detected in human prostate samples; 60% of the prostate cancer samples were positive for CYP4B1 mRNA while in non-cancerous prostate samples, only 50% were positive for CYP4B1 mRNA." (PMID 36768362, 2023).
steatosis (1 paper, 2024). Increased lipid within the cytoplasm of cells. "In human patients, the CYP4F12, CYP4F22, and CYP4V2 mRNA levels increase in steatosis and MASH, while the levels of CYP4B1, CYP4X1, and CYPZ1 mRNAs decrease in steatosis and MASH while the mRNA for these genes increases in HCC." (PMID 40452921, 2024).
Zinc deficiency (1 paper, 2022). A deficiency of the essential metal Zinc; an essential cofactor for many enzymes. "A previous study on rats found that zinc deficiency could result in the down-regulated the expression of the hepatic genes CYP4b1, CYP4A3, and CYP2C23, which are involved in xenobiotic metabolism." (PMID 35889856, 2022).
cancer (23 papers, 2011 to 2026). A tumor composed of atypical neoplastic, often pleomorphic cells that invade other tissues. "The association between CYP4B1 genetic polymorphism and susceptibility to prostate cancer, bladder cancer or other cancers has been reported." (PMID 37950293, 2023). "The high CYP4B1 expression increased the chances of bioactivation of carcinogenic aromatic amines, thereby leading to a high risk of cancer growth." (PMID 38041008, 2023). "Nevertheless, association of CYP4B1 expression patterns with various cancers and potential roles in cancer development have been reported for the human enzyme." (PMID 36768362, 2023). "The contribution of CYP4B1 in cancer is of particular interest as CYP4B1 gene expression has been found to be altered and presumably associated with certain cancers." (PMID 38041008, 2023). "Previous studies have reported that CYP4B1 polymorphisms are significantly correlated with the risk of various cancers, such as gastric cancer, bladder cancer, and lung cancer." (PMID 38041008, 2023). "The contribution of CYP4B1 gene polymorphisms has been studied in other cancers, such as bladder cancer, urothelial cancer, and lung cancer." (PMID 36307788, 2022). "CYP4B1 and its single nucleotide polymorphisms have been found to be involved in several cancers." (PMID 40405133, 2025). "This review will summarize the current status of CYP4B1 research with a spotlight on its roles in the metabolism of endogenous and exogenous compounds, structural properties, and cancer association, as well as its potential application in suicide gene approaches for targeted cancer therapy." (PMID 36768362, 2023). "Studies have shown that the alteration of CYP4B1 gene expression may be associated with certain cancers, suggesting that CYP4B1 may work in the development of cancer." (PMID 38041008, 2023). "Studies have shown that mutation in the CYP4B1 gene is considered to be a potentially cancer risk and may be involved in cancer by activating carcinogens, developing neovascularization and inducing inflammation." (PMID 36307788, 2022). "From a pathological perspective, CYP4B1 is believed to be involved in several types of cancer due to altered gene expression levels in tumor tissues compared to normal tissues." (PMID 40924729, 2025). "In cancer, CYP4B1 demonstrates the capability to activate procarcinogens and facilitate angiogenesis." (PMID 39010027, 2024). "CYP4B1 is expressed in various cancers and plays a role in cancer development via the activation of procarcinogens and neovascularization." (PMID 37639183, 2024). "Although there are reports on the roles of CYP4B1 in the initiation and progression of cancer, the picture is far away from being complete, and further investigations are needed." (PMID 36768362, 2023). "Studies have uncovered the role of CYP4B1 in the oxidation of fatty acids, activation of procarcinogens and neovascularization, and the promising potential as a target in cancer treatment." (PMID 36293001, 2022). "Studies have revealed that the human forms of CYP4B1 possess limited activity in vivo when compared with animals, rendering rabbit CYP4B1 a feasible gene therapy in humans to treat cancers in humans." (PMID 33592039, 2021). "The contribution of CYP4B1 in cancer is of particular interest, as its expression was found to be altered in a couple of specific cancers, including lung cancer." (PMID 33592039, 2021). "Mutations of CYP4B1, CYP4Z1, and other CYP4 genes that generate 20-HETE are a potential risk for cancer." (PMID 31480463, 2019). "Although the role of CYP4B1 is unclear in humans, in the cancer community, there is a potential therapeutic strategy involving prodrug activation by the CYP4B1 transgene." (PMID 30532780, 2018).
cancer (continued). "Since CYP4B1 metabolizes carcinogens, its function is especially important in the presence of multiple cancer-promoting factors." (PMID 21533263, 2011). "The CYP4B1, due to its ability to activate pro-carcinogens in rodent models, is capable of leading to the formation of DNA adducts and subsequent tumorigenesis; however, the role of CYP4B1 in human cancer is still not well understood." (PMID 40723371, 2025). "Aberrant expression of CYP4B1 in various cancers has attracted increasing research attention." (PMID 40924729, 2025). "The involvement of CYP4B1 in cancer has been implicated but has not been conclusively proven to date." (PMID 36768362, 2023). "Then, a prognostic index for all cancer was constructed by the formula MRG = expression level of BIRC5 × (−0.4126) + expression level of PLK1 × 0.39986 + expression level of CDKN3 × 0.2651 + expression level of CYP4B1 × (−0.0955)." (PMID 36293001, 2022). "Several studies have explored the role and significance of dysregulated CYP4B1 in human cancers." (PMID 33592039, 2021). "Therefore, CYP4B1 involvement in cancers has been suggested based on its expression levels and metabolism of pro-carcinogens in the bladder and lung." (PMID 31480463, 2019). "The study provides a comprehensive approach to the expression, clinical relevance, and genetic variation of the CYP4B1, CYP4F12, and CYP4F3 genes in breast and other cancers." (PMID 40723371, 2025). "The CYP4B1, CYP4F12, and CYP4F3 overall survival (OS) analyses were conducted using the TIMER2.0 in pan-cancer." (PMID 40723371, 2025). "Further analysis of the model genes within MOCM across pan‐cancer settings revealed that ANLN, CCNB1, CDKN3, EXO1, GJB3 and RAD51AP1 were predominantly overexpressed in tumour tissues, while GGT6 and CYP4B1 were highly expressed in normal tissues." (PMID 38958523, 2024). "Studies have suggested that CYP4B1 is a prognostic biomarker and potential therapeutic target of LUAD and can also be used as a target of cancer treatment." (PMID 36147484, 2022). "CYP4B1 was investigated in various malignancies, including uterine corpus endometrial carcinoma (UCEC), as a potential therapeutic target; however, its role in this type of cancer remained poorly characterized." (PMID 40723371, 2025). "CYP4B1, CYP4F12, and CYP4F3 gene expression levels were found to correlate with ESR1; then, a tumor versus normal tissue analysis and an overall survival evaluation in several types of cancer were conducted." (PMID 40723371, 2025). "The CYP4B1 and CYP4F14 genes were identified as significantly upregulated in the present study, which, in combination with previous reports, suggests that intestinal microbiota depletion may lead to inflammation and cancer in the body." (PMID 24718810, 2014). "As far as we are aware, RAB25 and CYP4B1 have been reported to be related to carcinomas, but it is not clear how the promoter methylations and mRNA expressions of RAB25 and CYP4B1 behave in ccRCC15,16." (PMID 29079774, 2017).
tumor (19 papers, 2017 to 2026). "Tumor stage: CYP4B1 rs3766197 was associated with the higher risk of advanced stages (III/IV stage) of BC under the heterozygote (OR = 1.57, 95% CI 1.04–2.38, p = 0.035) and over-dominant (OR = 1.61, 95% CI 1.05–2.46, p = 0.031) models." (PMID 38041008, 2023). "Further, stratified analysis was conducted to explore the association between CYP4B1 polymorphisms and BC risk in different subgroups based on age, smoking and drinking habits, BMI, and tumor location." (PMID 38041008, 2023). "Our results showed that CYP4B1 rs3766197 was also associated with BC risk according to stratified analysis by tumor stage." (PMID 38041008, 2023). "Moreover, CYP4B1 rs3766197 was related to the tumor stage, and the association of rs2297813 and rs12142787 with BC risk was related to reproductive number." (PMID 38041008, 2023). "The results showed that both the tumor tissue and the surrounding normal breast tissue expressed the enzymes CYP4B1 and others, such as CYP1B1, CYP2B6, CYP2C, CYP2D6, CYP2E1, and CYP11A1." (PMID 40723371, 2025). "Together, these findings provide robust experimental evidence supporting the tumor-suppressive function of CYP4B1 in LC." (PMID 40924729, 2025). "Functional assays revealed that the forced expression of CYP4B1 in ACC cell lines increased cell death and sensitivity to mitotane and cisplatin, suggesting a possible role for CYP4B1 in tumor suppression and chemosensitization." (PMID 40723371, 2025). "Our experiments establish CYP4B1 as a tumor suppressor in LC and a mitigator of pathological remodeling in HF." (PMID 40924729, 2025). "Functional assays, including cell invasion, migration, and colony formation, demonstrated that CYP4B1 overexpression markedly suppressed the malignant behavior of A549 and H1703 cells, supporting its tumor-suppressive role in LC." (PMID 40924729, 2025). "In normal and tumor cells, FAM83A and KRT6A were expressed higher in most tumor cells than in normal cells, while CYP4B1 was the opposite." (PMID 37081097, 2023). "In the TCGA-LUAD cohort, the results indicated that CYP4B1 mRNA expression was approximately 0.33-fold lower expressed in tumor tissues (n = 511) than in adjacent normal tissues (n = 59)." (PMID 33592039, 2021). "In contrast, CYP4B1 was significantly decreased compared with non-tumor tissues." (PMID 40405133, 2025). "Similarly, in the analysis of the CPTAC dataset in the UALCAN database, the protein expression levels of KRT6A and FAM83A were higher in the tumor group, while CYP4B1 was the opposite." (PMID 37081097, 2023). "As LUAD is a drug-resistant tumor, this finding could present CYP4B1 as an attractive future target for resistant-LUAD therapeutics." (PMID 33592039, 2021). "Additionally, the prognostic role of CYP4B1 indicated that it might act as a tumor-driven gene in LUAD." (PMID 33592039, 2021). "In the present study, except for the reduced expression of CYP4B1, the other eight DEGs were significantly increased in LUAD tumor tissues compared with normal tissues." (PMID 40405133, 2025). "For the univariate cox analysis of early prognostic genes (FAM83A, KRT6A, and CYP4B1) related to OS, DSS, DFI, and PFI of 32 tumors, we selected the top one to three with the lowest p-value in the analysis of tumor prognosis." (PMID 37081097, 2023). "We report that the CYP genes with highest expression, ranked by the mean expression in tumor tissues for all patients, are: CYP1B1 (mean normalized expression 112.8), CYP4Z1 (92.2), CYP2A6 (75.7), CYP4X1 (65.1), CYP4B1 (31.5), CYP2A7 (30.8), and CYP4F8 (11.6)." (PMID 28684774, 2017). "Finally, through RT-PCR and WB, we found that the expression levels of tumor cells (A549, H1975, and A549) in BESA-2B cells were significantly higher than those in FAM83A and KRT6A, while CYP4B1 was the opposite." (PMID 37081097, 2023). "By analyzing RNA-seq and microarray data of LUAD, CYP4B1 was found to demonstrate a remarkably lower expression in tumor specimens than in noncancerous lung tissues." (PMID 33592039, 2021).
tumor (continued). "On a genetic level, a comparable study in a set of 20 paired samples of tumour and adjacent normal breast tissues from patients with infiltrating ductal carcinoma identified the expression of CYP1B1, CYP2B6, CYP2C, CYP2D6, CYP2E1, CYP4B1 and CYP11A1 in both tumour and control tissues." (PMID 33809117, 2021). "The results indicated that the expression levels of (A) CYP4B1 and (B) CYP4F12 genes were higher (p < 0.05) in normal tissue than in tumor tissue, whereas (C) CYP4F3 expression levels were not significantly different." (PMID 40723371, 2025). "Since rabbit CYP4B1 (rCYP4B1), unlike hCYP4B1, is known to activate exogenous protoxins such as 4-IPO 25, resulting in highly toxic compounds, it has been considered a promising candidate for the clinical application of tumor-killing suicide gene systems." (PMID 36768362, 2023).
infection (2 papers, 2025). The state of being infected such as from the introduction of a foreign agent such as serum, vaccine, antigenic substance or organism. "Therefore, we expressed the cDNAs at similar multiplicity of infection (MOI) in HuH-7 cells and analyzed the puromycin resistant cells via immunoblotting with either an α-human CYP4B1 or an α-rabbit CYP4B1 antibody." (PMID 40577420, 2025).
bacterial diseases (1 paper, 2025). "In this study, flumequine, an antibacterial agent used to treat bacterial diseases, tended to increase the expression of CYP1A1, CYP1B1, CYP2B4, CYP2F2, and CYP4B1 following administration at a 4× dose compared to a 1× dose." (PMID 41227456, 2025).
myopathy (1 paper, 2024). A disease of the muscle in which the muscle fibers do not function properly. "We selected four up-regulated genes for general myopathy (MGST1, AOX1, FASN, PRKCD), CD163 for IBM, and CYP4B1 for titinopathy, aiming to validate their actual expression in our local muscles." (PMID 38600180, 2024).
CYP4B1 also shares sentences with these, for which no sentence is quoted: heart failure (3 papers); gastric cancer (2); adrenocortical adenomas (1); atherosclerosis (1); brain tumors (1); breast invasive carcinoma (1); breast tumors (1); depression (1); esophageal squamous cell carcinoma (1); hepatoma (1); Hypertension (1); liver cancer (1); liver fibrosis (1); Nephropathy (1); Obesity (1); stomach adenocarcinoma (1); urethral cancer (1).